PPFIA4 (PPFI scaffold protein A4)
Diseases named in the same sentence as PPFIA4 in open-access papers (continued):
Sharing a sentence is not in itself a finding about the gene and the disease.
cancer (9 papers, 2021 to 2025). A tumor composed of atypical neoplastic, often pleomorphic cells that invade other tissues. "PPFIA4, which encodes the protein liprin-α4, has been implicated in cancer-related processes such as glycolysis and immune regulation." (PMID 40991561, 2025). "The high expression of PPFIA4 was associated with reduced drug sensitivity of cancer cells to one drug (Dexrazoxane) and with increased drug sensitivity of cancer cells to three drugs (Idelalisib, Abiraterone, and IPI-145)." (PMID 36362375, 2022). "While being rarely studied, PPFIA4 has been reported in several studies to be potentially associated with aberrant metabolic processes, making it a gene of interest in cancer glycolysis." (PMID 34094943, 2021). "Due to the important role of this oncogene in cancer initiation and development, targeting PPFIA4 in cancer treatment studies can be considered." (PMID 38360831, 2024). "Under hypoxia, PPFIA4 can promote the proliferation of cancer cells via mitogen-activated protein kinase (MAPK) or phosphoinositide 3-kinase (PI3K) signaling pathways." (PMID 36605492, 2023). "The expression of PPFIA4 was found in 26 of the 62 carcinoma samples (41.9%), whereas the remaining 36 samples (58.1%) were negative." (PMID 35924146, 2022). "Compared to other members of the PPFIA family, PPFIA4 has rarely been studied thus far, and our search for PPFIA4 on PubMed has yielded 10 articles, only one of which is on PPFIA4 and cancer." (PMID 34094943, 2021). "More importantly, we showed that PPFIA4 was involved in the regulation of glycolysis, and silencing PPFIA4 attenuated glycolysis, suppressed cancer cell proliferation, migration and invasion." (PMID 34094943, 2021). "Then we confirmed that PPFIA4 overexpression was characteristic of many cancers." (PMID 34094943, 2021). "However, our data are limited to in vitro studies and further in vivo studies are needed to confirm the efficacy of PPFIA4 silencing in cancer suppression and survival improvement in human tissues and/or animal models." (PMID 34094943, 2021). "The PPFIA4 protein liprin-α4 is involved in the MAPK signalling pathway which may cause castration-resistant PCa through AR pathway independence, and has been proposed as a potential therapeutic target for several cancer types." (PMID 37749167, 2024). "Materials and methods: In this study, several databases, including Oncomine, UALCAN, and the cancer cell line encyclopedia, were used to compare differences in PPFIA1, PPFIA2, PPFIA3, and PPFIA4 expression between normal colon samples and CRCs." (PMID 36605492, 2023). "Novel to this study, we identify ANO7 as a potential oncogenic driver in African men, through the formation of gene fusions with the cancer-related genes G3BP1 and PPFIA4, involved in androgen receptor (AR) and mitogen-activated protein kinase (MAPK) signalling, respectively." (PMID 37749167, 2024).
PPFIA4 also shares sentences with these, for which no sentence is quoted: small cell lung carcinoma (2 papers); thyroid cancer (2); colorectal adenocarcinoma (1); Dystonia (1); infection (1); lipoma (1); lymphatic malformation (1); metastatic colorectal cancer (1); neurodegenerative disease (1); Parkinson disease (1); pilocytic astrocytoma (1); renal cell carcinoma (1).